CCDC183 (coiled-coil domain containing 183)
Synonyms: KIAA1984; MGC15438; bA216L13.7; PARF
Tractability: No criterion of Open Targets' tractability assessment is met for any kind of drug.
Gene: Protein-coding gene on chromosome 9 (136,796,338 to 136,807,741, forward strand). Ensembl gene ENSG00000213213.
Subcellular location (Human Protein Atlas): Cytosol; Nucleoplasm; Mid piece; Primary cilium tip
Genetic constraint (gnomAD): Loss-of-function variants: 66 observed, 66.11 expected, observed/expected ratio (o/e) 1, 90% interval 0.82 to 1.23. The synonymous counts are far from expectation, so gnomAD's model fits this gene poorly and the ratio says little. Missense variants: 769 observed, 668.77 expected, observed/expected ratio (o/e) 1.15, 90% interval 1.08 to 1.22. Synonymous variants: 323 observed, 267.41 expected, observed/expected ratio (o/e) 1.21, 90% interval 1.1 to 1.32.
Homologues: Orthologues: chimpanzee CCDC183 (97% identical), macaque CCDC183 (93% identical), guinea pig CCDC183 (71% identical).
Diseases named in the same sentence as CCDC183 in open-access papers:
CCDC183 is named in the same sentence as 7 diseases in open-access papers, as found by Europe PMC text mining. Sharing a sentence is not in itself a finding about the gene and the disease. The quoted sentences say what the papers report.
Infertility (2 papers, 2023). "To reveal the cause(s) of the infertility of the Ccdc183 KO male mice, we examined spermatozoa obtained from Ccdc183 KO cauda epididymis." (PMID 37882665, 2023).
male infertility (2 papers, 2023). The inability of the male to effect fertilization of an ovum after a specified period of unprotected intercourse. "Multiple studies have reported a relationship between CCDC183 and male infertility, but the functions of CCDC183 have not been described owing to the lack of KO animal models." (PMID 37882665, 2023). "We demonstrated that the absence of CCDC183 causes male infertility with morphological and motility defects in spermatozoa." (PMID 37882665, 2023). "We demonstrate our analyses’ potential to identify novel highly germ cell–specific markers (TSPY4 and LUZP4 for spermatogonia; HMGB4 for round spermatids) and identified putatively misregulated genes in male infertility (RWDD2A, CCDC183, CNNM1, SERF1B)." (PMID 36446526, 2023). "In the present study, we demonstrated that absence of CCDC183 induces male infertility with morphological and motility defects in spermatozoa." (PMID 37882665, 2023).
thyroid cancer (1 paper, 2023). "We found five TAD blocks with CoMut genes/events specific to ATC with certain mutation frequency in The Cancer Genome Atlas Thyroid Cancer (TCGA-THCA) cohort, including CoMut pairs MAST/NSUN4, AM129B/TRUB2, COL5A1/PPP1R26, PPP1R26/GPSM1/CCDC183, and PRAC2/DLX4." (PMID 36609218, 2023).
cancer (1 paper, 2023). A tumor composed of atypical neoplastic, often pleomorphic cells that invade other tissues. "The coiled-coil domain containing 183 (CCDC183) gene is primarily expressed in human testis, suggesting it may act as a cancer testis antigen." (PMID 37038005, 2023). "Elevated expression of the testis-specific CCDC183 gene in patients who experienced PR/SD suggests that a possible cancer testis antigen (CTA) may be present in pediatric cancers." (PMID 37038005, 2023).
tumor (1 paper, 2023). "Differential gene expression analysis revealed elevated expression of CALCA (preprocalcitonin) and CCDC183 (highly expressed in testes) in patients who experienced clinical activity, suggesting that tumor neoantigens from these genes may contribute to immune response." (PMID 37038005, 2023).
CCDC183 also shares sentences with these, for which no sentence is quoted: bladder cancers (1 paper); breast carcinoma (1).